LINC00393 (long independently transcribed non-coding RNA 393)
Gene: Long non-coding RNA gene on chromosome 13 (73,412,982 to 73,662,210, reverse strand). Ensembl gene ENSG00000224853.
Diseases named in the same sentence as LINC00393 in open-access papers:
LINC00393 is named in the same sentence as 3 diseases in open-access papers, as found by Europe PMC text mining. Sharing a sentence is not in itself a finding about the gene and the disease.
LINC00393 shares sentences with these, for which no sentence is quoted: cervical cancer (1 paper); diabetes (1); Obesity (1).